ANXA2 (annexin A2)
Diseases named in the same sentence as ANXA2 in open-access papers (continued):
Sharing a sentence is not in itself a finding about the gene and the disease.
breast carcinoma (continued). "Taken together, our survival analysis confirms that high expression of circulating exo-AnxA2 in serum results in a poor survival of the breast cancer patients and suggests that the circulating exo-AnxA2 could predict prognosis of breast cancer patients." (PMID 31992335, 2020). "The results demonstrated that breast cancer patients with high levels of serum exo-AnxA2 (n = 85) had significantly shorter OS (hazard ratio 2.802; 95% CI = 1.030–7.620; log-rank P = 0.0353) than those with low levels of serum exo-AnxA2 (n = 84)." (PMID 31992335, 2020). "We previously showed that AnxA2 is present in exosomes derived from the breast cancer cells." (PMID 31992335, 2020). "The level of serum AnxA2 in different breast cancer subtypes differed significantly." (PMID 33374917, 2020). "Furthermore, priming of animals with breast cancer-derived exosomes containing high annexin A2, led to an increased level of VEGFR1 in lung and brain sections, with a concordant increase in MMP9 in tissues." (PMID 31555295, 2019). "Moreover, Anxa2 confers increased invasiveness in breast cancer; Anxa2 knockdown also inhibits migration and invasion in nasopharyngeal carcinoma." (PMID 31113450, 2019). "To determine whether Rack1 is necessary for Anxa2 tyrosine phosphorylation, we silenced the expression of Rack1 in two drug-resistant breast cancer cell lines using two different Rack1-specific siRNAs." (PMID 31113450, 2019). "Accordingly, we first studied the functions of ANXA2 in breast cancer." (PMID 31695775, 2019). "We next explored the function of the LncCCAT1/ANXA2 complex in breast cancer." (PMID 31695775, 2019). "Throughout the years of investigation Annexin A1 (AnxA1), Annexin A2 (AnxA2), Annexin A3 (AnxA3), Annexin A4 (AnxA4), Annexin A5 (AnxA5), Annexin A6 (AnxA6), and Annexin A8 (AnxA8) have all been identified as potential modulators of breast cancer progression." (PMID 29416802, 2018). "ANXA2, as a tumor-associated protein, promotes cancer progression including proliferation, invasion, and metastasis in various cancer types (NPC, ovarian cancer, gliomas, hepatomas, pancreatic cancer, and breast cancer)." (PMID 29598816, 2018). "The protein ANXA2 could be bind to a well-known multidrug-efflux transporte named P-gp, which promoted the invasiveness of multidrug-resistant breast cancer cells through regulation of ANXA2 phosphorylation." (PMID 29291003, 2017). "ANXA2 also mediates adhesion of breast cancer cells to microvascular endothelial cells." (PMID 28720835, 2017). "Anxa2 is proven to be a tumor promoter in breast cancer progression." (PMID 27754360, 2016). "Recently, Shetty and colleagues observed that galectin-3 promotes cell migration through its association with annexin A2 (AnxA2) on the plasma membrane of HER-2 negative breast cancer cells." (PMID 27242966, 2016). "In this study, the expression pattern of Anxa2 in breast cancer tissues was investigated." (PMID 26307676, 2015). "Given the important function of EGFR signaling in EMT induction in breast cancer, we speculate that Anxa2 promotes EMT via the activation of the EGF/EGFR pathway." (PMID 26307676, 2015). "Similarly, Anxa2 depletion reduced breast cancer migration and invasion in vitro and metastatic potential of T47D cells in an SCID mouse model in vivo." (PMID 26307676, 2015). "Consistently, in the present study, re-expression of the phosphor-mimicking mutant Anxa2 (Anxa2 Y23D), but not the phosphorylation-deficient Anxa2 (Anxa2 Y23A), in Anxa2-silencing breast cancer cells rescued EGF-induced EMT." (PMID 26307676, 2015). "Moreover, ANXA2 appears to be involved in the drug resistance phenotype of cancer cells based on the finding that ANXA2 is upregulated during acquisition of the multi-drug resistance phenotype in breast cancer cells." (PMID 25611381, 2015). "We also showed that upregulated Anxa2 expression could be used as a predictor of poor prognosis for breast cancer patients." (PMID 26307676, 2015).
breast carcinoma (continued). "Nevertheless, the mechanism through which Anxa2 promotes EGF-induced EMT in breast cancer cells remains unknown." (PMID 26307676, 2015). "Similarly, ANXA2 is highly expressed in the breast cancer cell line MDA-MB231 (highly invasive) compared with MCF-7 (poorly invasive)." (PMID 24591759, 2014). "Abnormal ubiquitination of ANXA2 may promote the metastasis and infiltration of breast cancer cells by inducing high levels of ANXA2 expression." (PMID 24591759, 2014). "ANXA2-dependent, localized plasmin generation by human breast cancer cells could contribute to angiogenesis and metastasis." (PMID 24591759, 2014). "Clinically, annexin A2 may act as a predictor of pathological response to neoadjuvant chemotherapy in advanced breast cancer patients." (PMID 23519104, 2013). "Materials and methods: Exosomes isolated from conditioned media of MCF10A (non-malignant) and MCF10CA1A (malignant) were characterised by Western blotting and Nanotrac Analyzer, TEM and AFM to study the correlation between exosomal AnxA2 and the breast cancer progression." (PMID 26082317, 2013). "To test whether the phosphorylation of Anxa2 at Tyr23 is important for the proliferation and invasion of breast cancer SK-BR-3 cells, we generated a panel of plasmids pEGFP-N3-Anxa2WT, pEGFP-N3-Anxa2Y23A, and pEGFP-N3-Anxa2Y23D." (PMID 23691485, 2012). "The increase in EGFR, Src and AnxA2 levels upon Her-2 downregulation and inhibition led us to investigate the role of AnxA2 in EGFR signaling in TNBC subset of breast cancer, where EGFR plays a major role in survival, growth, migration and invasion of cancer cells." (PMID 22957061, 2012). "However, little is known about the effects of Tyr23 phosphorylation of Anxa2 on the proliferation and invasion abilities of breast cancer cells and on the localization of the phosphorylation signal transducer and activator of transcription (Stat3)." (PMID 23691485, 2012). "Moreover, our findings indicate that the expression of AnxA2 correlates with the aggressiveness of breast cancer and substantiates its prospects as a prognostic marker." (PMID 22957061, 2012). "Annexin A2 (Anxa2), a member of the Annexin family of calcium-dependent phospholipid binding proteins, was reported to be abundantly expressed in many cancer tissues and is believed to play an important role in tumorigenesis and breast cancer progression." (PMID 23691485, 2012). "However, the roles of P-gp and Anxa2 in regulating the migration and invasion of breast cancer cells still need further investigation." (PMID 23691462, 2012). "Tyr23 phosphorylation of Anxa2 could activate Stat3 and phosphorylation Stat3 localization in the nucleus of breast cancer SK-BR-3 cells." (PMID 23691485, 2012). "The interaction of Anxa2 with P-pg may play an important role in the enhanced invasiveness of MDR human breast cancer cells." (PMID 23691462, 2012). "Annexin A2 shows increased expression in several type of cancer, including renal cell cancer, breast cancer and sarcomas, and there are several possible mechanisms by which annexin A2 may be involved in tumour progression." (PMID 18071363, 2008). "Such novel findings accentuate the fact that annexin A2 might be considered a therapeutic target antigen for ovarian cancer, as well as breast cancer; however, broader preclinical and substantiated clinical evidence is required before confidently classifying this antigen as a potential target." (PMID 38146364, 2023). "Our findings suggest a mechanism for the poor clinical outcomes associated with a desmoplastic TME as we hypothesize that the high expression of collagen-I seen in desmoplasia can increase the invasive capacity of breast cancer cells via its regulation of Annexin A2." (PMID 37941562, 2023).
breast carcinoma (continued). "We hypothesized that interactions between members of the annexin family and FetuA should prevent osteoblast-mediated mineralization, similarly as in the case of interactions of FetuA with AnxA2 in VSMCs as well as or with AnxA2 and AnxA6 in breast carcinoma cells." (PMID 33924370, 2021). "A cellular thermal shift assay verified the intracellular interaction between Anxa2 and (20S)G-Rh2: an immuno-precipitation as well as NF-κB luciferase reporter assay confirmed the inhibitory impact on NF-κB by (20S)G-Rh2 in breast cancer cell line MDA-MB-231 and MCF-7." (PMID 32244350, 2020). "Therefore, we investigated whether AnxA2 is expressed in exosomes isolated from the serum samples of breast cancer patients." (PMID 31992335, 2020). "Furthermore, the results of the present study showed that circulating serum AnxA2 levels had the potential to distinguish breast cancer patients from normal healthy females, which suggest the potential value of serum AnxA2 as a diagnostic biomarker for breast cancer." (PMID 33374917, 2020). "However, whether Anxa2 is involved in EMT induction in breast cancer or other types of tumors remains unknown." (PMID 26307676, 2015). "Furthermore, ANXA1 or ANXA2 mRNA or protein levels are altered in various human diseases, for example, cystic fibrosis, hepatocellular carcinoma, prostate carcinoma, pancreatic cancer, breast cancer, and renal cell carcinoma." (PMID 24591769, 2014). "Moreover, anti-annexin A2 antibodies have been shown to inhibit pancreatic cancer metastasis in a mouse model of pancreatic ductal adenocarcinoma and to inhibit tumor growth in breast cancer and Lewis Lung Carcinoma xenograft mouse models." (PMID 23945256, 2013). "To further investigate the interaction between ANXA2 and SPOCK1, we constructed GARS-knockdown breast cancer fibroblasts using ANXA2-specific siRNA." (PMID 40837013, 2025). "Currently, a small molecular function inhibitor of ANXA2, 5α-epoxyalantolactone (5α-EAL) is expected to become an effective treatment for breast cancer." (PMID 38658569, 2024). "Subsequently, the overexpression of ANXA2 was reported in various tumors, such as hepatocellular carcinoma (HCC) and breast cancer." (PMID 39057791, 2024). "ANXA2 has previously been demonstrated to activate STAT3 in macrophages and enhance the formation of breast cancer, pancreatic cancer and hepatoma." (PMID 36916296, 2023). "We found that AQP1 recruited ANXA2 to the Golgi apparatus, promoted Golgi apparatus extension, and induced secretion of ICAM1 and CTSS, which induced breast cancer cell invasion." (PMID 36803413, 2023). "We highlight two examples of previously unannotated cancer-cell-specific enhancers of ANXA2 and PRDX4 gene expression and show evidence for super-enhancer regulation of LAMB3 and CD47 in male breast cancer cells." (PMID 37685859, 2023). "Interestingly, a study in breast cancer indicated that the expression level of serum exosomal-annexin A2 (exo-AnxA2) could be detected higher in women with carcinoma compared with non-cancer, particularly for triple-negative breast cancer (TNBC) rather than luminal or HER2-positive breast cancer." (PMID 37875600, 2023). "Correlation analysis using 194 IDC patients or the GEPIA database indicated that AQP1 was positively correlated with ANXA2, Rab1b, CTSS, and ICAM1 in breast cancer patients." (PMID 36803413, 2023). "To explore the impact of annexins in breast cancer, we compared the expression of ANXA1, ANXA2 and ANXA4 in MDA-MB-231 and MCF7 cells at the protein and mRNA level." (PMID 38092984, 2023). "Increased tyrosine phosphorylation of annexin A2 promotes proliferation, invasion, and STAT3 phosphorylation in breast cancer cells." (PMID 35646067, 2022). "Sayantan found that exosomal annexinA2 (AnxA2) promotes angiogenesis and activates the p38, nuclear factor kappa-B (NF-ĸB) and STAT3 pathways to create a PMN that induces breast cancer lung and brain metastasis." (PMID 36096820, 2022).
breast carcinoma (continued). "Silencing ANXA2 was shown to downregulate S100A10 and to inhibit breast cancer proliferation and invasion." (PMID 35631574, 2022). "It is reported that ANXA2 enhances STAT3 activation and promotes proliferation and invasion of breast cancer cells." (PMID 35646067, 2022). "Annexin A2 (ANXA2) was found to be selectively and differentially co‐immunoprecipitated with EpCAM in the ERα+ breast cancer cells MCF‐7 and ZR‐75‐1." (PMID 34240826, 2022). "Another report showed ANXA2 binds to STAT3 and promotes epithelial to mesenchymal transition in breast cancer cells." (PMID 35646067, 2022). "Our previous analysis of the Cancer Genome Atlas (TCGA) cohort of 113 TNBC patients showed a poor survival rate due to high AnxA2 tissue mRNA expression compared to ER-positive, PR- positive, and HER2-positive breast cancer patients." (PMID 36612209, 2022). "It is pointed out that ANXA2 overexpression in NSCLC 59, HCC 105, serous ovarian cancer 106, biopsies of epithelial ovarian cancer 107, urothelial carcinoma 108, breast cancer 109, 110 and nasopharyngeal carcinoma (NPC) 84 was associated with poor prognosis." (PMID 33995636, 2021). "In breast cancer, studies have proven that ANXA2, ANXA4, ANXA5, ANXA6, and ANXA7 are required for repair in breast cancer cells, indicating that a network of annexins participate in the plasma membrane repair response." (PMID 34484309, 2021). "The expression of serum AnxA2 levels in ER+, HER2+ and TNBC breast cancer patients were analyzed by ELISA assay." (PMID 33374917, 2020). "The median expression value of serum exo-AnxA2 in breast cancer patients (n = 107) was used for DFS evaluation and stratified into high exo-AnxA2 (> 70.87 ng/mL) and low exo-AnxA2 groups (< 70.87 ng/mL)." (PMID 31992335, 2020). "High expression of exo-AnxA2 levels in breast cancer patients exhibited worse OS and DFS, suggesting that the level of serum exo-AnxA2 has an important predictive value in breast cancer prognosis." (PMID 31992335, 2020). "This is further compacted by our findings of a significant correlation between Annexin A2 and EGFR expression and by the observation that breast cancers found to have EGFR overexpression are more commonly ER negative than ER positive." (PMID 32629869, 2020). "Following identification and verification of Annexin A2 as a protein newly synthesized in EGF mediated MDA-MB-231 cell migration and invasion, we next examined its expression profile across a number of breast cancer cell lines." (PMID 32629869, 2020). "We showed that Rack1 and Anxa2 are required for the invasive and metastatic potential of multidrug-resistant (MDR) breast cancer cells." (PMID 31113450, 2019). "Previous studies showed that ANXA2 modulates STAT3 phosphorylation (p-STAT3) levels to stimulate proliferation, angiogenesis, metastasis and epithelial to mesenchymal transition in breast cancer cells." (PMID 30898167, 2019). "ANXA2 promotes the invasion and metastasis of different cancers (ovarian cancer, HCC, gliomas, pancreatic cancer, renal cell carcinoma, lung cancer, breast cancer, and NPC)." (PMID 29598816, 2018). "Here, we show 2448 targets a unique glycan epitope on annexin A2 (ANXA2) and can potentially monitor the Epithelial-Mesenchymal Transition (EMT) in ovarian and breast cancer." (PMID 29568351, 2018). "We previously reported that P-gp activity regulates Anxa2 phosphorylation and promotes the invasiveness of MDR breast cancer cells." (PMID 27754360, 2016). "We previously showed that P-gp binds to Anxa2 and promotes the invasiveness of MDR breast cancer cells through regulation of Anxa2 phosphorylation." (PMID 27754360, 2016). "To confirm that MIEN1 regulates AnxA2 dependent plasmin generation, we investigated the effects of MIEN1 ablation either alone or in combination with AnxA2 plasmin generation in breast cancer cells." (PMID 26272794, 2015). "Altogether, our results indicated a direct interaction between Anxa2 and STAT3 in breast cancer cells." (PMID 26307676, 2015).
breast carcinoma (continued). "A strong positive correlation was found between Anxa2 and EGFR overexpression in breast cancer tissues." (PMID 26307676, 2015). "In human breast cancer tissues, phospho-STAT3 expression was upregulated in the Anxa2 high expression group." (PMID 26307676, 2015). "Knockdown of Anxa2 also impaired EGF-induced EMT, as well as breast cancer cell invasion in vitro and metastatic potential in vivo." (PMID 26307676, 2015). "In conclusion, our study demonstrates that Anxa2 expression is positively correlated with the expression of EGFR and EMT markers in breast cancer tissues and cell lines." (PMID 26307676, 2015). "Colocalization experiments using confocal microscopy also confirmed interaction of endogenous AnxA2 and MIEN1 primarily in the cytosol, plasma membrane and the perinuclear area of breast cancer cells." (PMID 26272794, 2015). "In fact, annexin A2 mediates tPA-dependent plasmin generation (probably through S100A10) and promotes the in vitro migration of MDA-MB-231 breast cancer cells." (PMID 23519104, 2013). "It has been reported previously that cleavage of annexin A2 at lysine 10 by MMP-7 can assist tumor invasion and metastasis of colorectal and breast cancer cell lines." (PMID 23945256, 2013). "Based on these findings, we hypothesize that in breast cancer, SPOCK1-positive CAFs may involve a synergistic interaction between ANXA2 and SPOCK1 to regulate tumor EMT and metastasis." (PMID 40837013, 2025). "The expression level of Annexin A2 on EVs was significantly higher in the serum of breast cancer patients than in that of non-cancer patients." (PMID 38111675, 2023). "Interestingly, we observed that one set of proteins was identified more frequently, with HLA-A, HLA-B, A2M, ACTB, ALDOA, ANXA2, and FN1 identified in at least 13 of 22 studies that explored the vesicular proteome in breast cancer." (PMID 37629204, 2023). "Analyses of clinical samples revealed that the levels of ANXA2 are higher in EVs derived from the sera of breast cancer patients than in women without cancer." (PMID 36835116, 2023). "In fact, ANXA2 downregulation and ANXA8 upregulation were jointly sufficient to create abnormal ductal carcinoma in situ (DCIS) acinar-like structures, which resemble early breast cancer lesions." (PMID 36247003, 2022). "We, therefore, speculate that ANXA2, HSPB1, and TIMP1, may be among the genes induced by ZEB1 during early/partial EMT stages that may change the tissue tropism of ERα+ breast cancer cells." (PMID 35440541, 2022). "AnxA2 has also been characterized as a biomarker in HER2 and luminal B breast cancer." (PMID 36612209, 2022). "Other studies proved the higher expression of serum exosomal annexin A2 (AnxA2) in breast cancer patients, compared to non-cancer females (p < 0.0001), especially for TNBC, rather than luminal and HER2+ breast cancer." (PMID 35565189, 2022). "Overexpression of ANXA2 detected both in herceptin resistant and Her-2 negative breast cancer cells." (PMID 33995636, 2021). "High-expression of Anxa2 could directly regulate STAT3 and consequently enhance the invasion and metastasis in breast cancer cells." (PMID 33903672, 2021). "Precipitated by anti-myc antibody, Anxa2-dN failed to interact with p50, demonstrating Anxa2 bound to p50 via its N-terminus in breast cancer cells as does in Hepatoma cells." (PMID 32244350, 2020). "Here, we show that the expression of AnxA2 was high in tumor tissues and serum samples of breast cancer patients compared to non-cancer patients." (PMID 33374917, 2020). "Here, we further compared the expression of exo-AnxA2 levels in sera of AA and CA with breast cancer and non-cancer females." (PMID 31992335, 2020). "In addition, we also determined the correlation between exo-AnxA2 levels in the serum and DFS of the breast cancer patients." (PMID 31992335, 2020).